MIR4444-1 (microRNA 4444-1)
Synonyms: hsa-mir-4444; miR-4444-1; MIR4444; hsa-mir-4444-1
Gene: MicroRNA gene on chromosome 2 (177,212,726 to 177,212,799, forward strand). Ensembl gene ENSG00000284252.
Homologues: Orthologues: chimpanzee MIR4444-1 (100% identical). Paralogues in human: MIR4444-2 (100% identical).